TMPRSS2 (transmembrane serine protease 2)
Diseases named in the same sentence as TMPRSS2 in open-access papers (continued):
Sharing a sentence is not in itself a finding about the gene and the disease.
prostate carcinoma (continued). "Additionally, PARP inhibition was associated with radiosensitization of TMPRSS2-ERG-positive prostate cancer cells." (PMID 26684754, 2015). "Furthermore, in our experiments, the VCaP cell line was found to be representative of the prostate cancer biopsies, since it expressed the most frequent variants of TMPRSS2-ERG fusion oncogene found in patients, namely variants III and IV." (PMID 25933120, 2015). "In addition, urine TMPRSS2-ERG levels seem to be associated with indicators of clinically significant prostate cancer at biopsy and prostatectomy such as Gleason score, the percent of tumor observed, and number of cores with tumor." (PMID 26317031, 2014). "Somatic mutations in prostate cancer gives rise to chromosomal rearrangements that juxtapose the coding sequence of an ETS family transcription factor gene (most commonly ERG or ETV1) next to the androgen –related TMPRSS2 promoter." (PMID 24063260, 2013). "TMPRSS2-ERG cooperates with loss of PTEN to further promote prostate cancer progression." (PMID 21731703, 2011). "Loss of PTEN expression has been strongly associated with prostate cancer progression and has recently been implicated as cooperating with TMPRSS2–ERG fusion in high-grade prostatic intraepithelial neoplasia." (PMID 20068566, 2010). "Regarding influence of sex, TMPRSS2 expression is upregulated by androgens and has been associated with risk for prostate cancer, suggesting the predominance of COVID-19 infection in males could be partially explained by increased TMPRSS2 expression in this sex." (PMID 36672770, 2022). "Work from us and others has shown that old age, comorbidities such as diabetes and hypertension, behavioral factors like smoking, and molecular factors like androgen receptor signaling and TMPRSS2 may contribute to the increased risk of COVID-19 for prostate cancer patients." (PMID 33915795, 2021). "Indeed, TMPRSS2-ERG fusion is associated with 40–70% of prostate cancer." (PMID 32974166, 2020). "Interestingly, however, by using available Italian exome studies, four SNPs were found to differ in Italian population compared with East Asians with the missense substitution p.Val160Met already associated with genomic rearrangement of TMPRSS2 as risk factor of prostate cancer." (PMID 32774170, 2020). "Thus, loss of miR-145 may provide a TMPRSS2-ERG gene fusion-independent means to up-regulate ERG expression in prostate cancer." (PMID 27208692, 2016). "The main objective of the current study was to determine whether the TMPRSS2-ERG gene fusion was associated with prostate cancer-specific mortality in tumors from 372 patients ascertained from a population-based cancer registry and with long-term surveillance after cancer diagnosis." (PMID 18694509, 2008). "The TMPRSS2:ERG gene fusion is a truncal oncogenic event in a large subset of prostate cancers, yet its clinical relevance has remained unclear." (PMID 41837288, 2026). "Approximately 50% of prostate cancer (PCa) patients harbor fusions involving the TMPRSS2 and ERG genes." (PMID 42120493, 2026). "TMPRSS2 is involved in respiratory viruses and prostate cancer, providing prospects for treatment techniques targeting viral infections and malignancies." (PMID 40297833, 2025). "In prostate cancer, TMPRSS2 gene alterations serve as important biomarkers, with TMPRSS2-ETS gene fusions (particularly TMPRSS2-ERG) occurring in approximately 50% of cases and associated with aggressive disease features." (PMID 41150771, 2025). "The prognostic significance of TMPRSS2: ERG fusions in prostate cancer has been debated since the identification of this alteration in the disease." (PMID 40332161, 2025). "These authors showed that during prostate cancer progression, TMPRSS2 plays a role in matriptase activation." (PMID 41408854, 2025).
prostate carcinoma (continued). "TMPRSS2-ERG (T2E) is a gene fusion present in approximately 50% of prostate cancer cases and represents one of the most common genetic alterations observed in patients with this type of cancer." (PMID 41374944, 2025). "TMPRSS2 is one of the target genes of the AR, and when androgens stimulate TMPRSS2-ERG fusion-positive prostate cancer cells, a significant increase in ERG expression can be observed." (PMID 39963114, 2025). "Together, these studies indicate that TMPRSS2 proteolytically activates its substrates (such as matriptase) to promote prostate cancer progression via an increase in tumor growth, invasion, and metastasis." (PMID 40214422, 2025). "Our study provides novel evidence that androgen deprivation therapy in prostate cancer patients significantly reduces TMPRSS2 expression in lung tissue." (PMID 41150771, 2025). "This study demonstrates that androgen deprivation therapy (ADT) significantly reduces TMPRSS2 expression in the lung tissue of prostate cancer patients, with direct AR antagonists exerting the most pronounced effect." (PMID 41150771, 2025). "The authors further demonstrated that TMPRSS2 promotes the growth of LNCaP prostate cancer in nude mice and that TMPRSS2 promotes invasion of LNCaP prostate cancer via proteolytic activation of matriptase." (PMID 40214422, 2025). "ERG and other ETS family transcription factors are over-expressed in half of human prostate cancers as a result of fusions with the promoter sequence of the androgen receptor (AR)-dependent TMPRSS2 gene." (PMID 40332161, 2025). "In 2005, researchers identified the TMPRSS2 (transmembrane serine protease 2)-ERG (ETS-related gene) fusion gene in prostate cancer for the first time." (PMID 40584293, 2025). "The authors further showed that TMPRSS2 promotes invasion and metastasis of prostate cancer in TRAMP mice." (PMID 40214422, 2025). "TMPRSS2 is commonly linked to carcinogenesis by its involvement in gene fusions with the ERG gene; TMPRSS2–ERG fusion is the most prevalent chromosomal abnormality in prostate carcinoma." (PMID 40297833, 2025). "In prostate cancer, the most common gene fusion event is the fusion between the promoter region of TMPRSS2 and the coding region of the ERG gene." (PMID 40332527, 2025). "Studies have shown that the elevated expression of the ERG oncogene in prostate cancer patients is due to its fusion with transmembrane protease serine 2 (TMPRSS2)." (PMID 40243658, 2025). "The TMPRSS2:ERG fusion represents the most common genomic alteration in prostate cancer, occurring in almost half of all prostate cancers especially in younger patients." (PMID 40554389, 2025). "Future studies are required to investigate the contributions of TMPRSS2 to the survival of prostate cancer." (PMID 40214422, 2025). "This reduction has been reported to contribute to more aggressive cancer forms, for example, as shown in TMPRSS2-ERG-negative prostate cancer." (PMID 40724805, 2025). "One major category of molecular changes involves ETS gene fusions, particularly TMPRSS2-ERG, present in nearly 50% of prostate cancers and associated with distinct transcriptional programs." (PMID 40565559, 2025). "In the context of cancer, especially prostate cancer (PCa), TMPRSS2 is of particular interest due to its androgen‐regulated expression and involvement in oncogenic processes." (PMID 40145441, 2025). "Holly et al105 observed that obesity impacted the prognosis of patients with TMPRSS2-ERG fusion gene-positive prostate cancer." (PMID 40584293, 2025). "The TMPRSS2::ERG fusion is one of the most frequent genomic alterations in prostate cancer and contributes to oncogenic transformation, particularly when combined with PTEN loss." (PMID 41267989, 2025). "Several urinary biomarkers for prostate cancer have also been described, which include urinary measurements of prostate cancer gene 3, Transmembrane protease serine 2 genes (TMPRSS2: ERG) and SelectMDX test." (PMID 40264829, 2025).
prostate carcinoma (continued). "Studies have shown that the TMPRSS2-ERG fusion gene has a prevalence of up to 50% in prostate cancer." (PMID 40584293, 2025). "We evaluated the impact of ADT on pulmonary TMPRSS2 expression in prostate cancer patients and analyzed differences in expression patterns associated with specific ADT regimens." (PMID 41150771, 2025). "Chromosomal deletions represent the next most common recurrent genomic alterations in prostate cancer after TMPRSS2:ERG fusions." (PMID 40554389, 2025). "The EWSR1-ETS Ewing loops appear to be less complex than TMPRSS2:ERG prostate cancer loops with fewer rearrangements (two to ten rearrangements in one or two loops)." (PMID 40332527, 2025). "TMPRSS2‐ERG is a gene fusion that is commonly found in prostate cancer, which denotes the fusion of the regulatory region of the androgen‐regulated gene TMPRSS2 to the coding region of the oncogene ERG." (PMID 38379333, 2024). "The relationship between TMPRSS2 and carcinogenesis has been clearly defined in prostate cancer and it has been emphasized that it plays an important role in androgen signaling." (PMID 39350850, 2024). "TMPRSS2‐ERG fusion is a relatively common event seen in prostate cancer, which can be found in up to 50% of cases." (PMID 38379333, 2024). "The metabolomic characteristics of prostate cancer include heightened Fatty Acid Synthase (FAS)-mediated fatty acid metabolism and uptake, particularly in Transmembrane Protease, Serine 2 (TMPRSS2)-Ets variant 1 (ERG) translocation-positive samples." (PMID 38791108, 2024). "These contradictions can be attributed to the racial and genetic differences in the molecular pathogenesis of prostate cancer among the different races with Africans more likely to have TMPRSS2-ERG gene fusion through deletion." (PMID 38730435, 2024). "Chromoplexy is particularly prevalent in prostate cancer and frequently generates TMPRSS2-ERG driver fusions." (PMID 38286829, 2024). "ETV1 plays a key role in mediating androgen metabolism and is frequently over expressed in advanced prostate cancer, where chromosomal rearrangements (TMPRSS2 fusion) are common." (PMID 38667288, 2024). "The prostate cancer–specific TMPRSS2-ERG gene fusion has also been seen in approximately 50% of cases, similar to the rate in adenocarcinoma, further supporting a luminal prostate cell of origin." (PMID 39318975, 2024). "In prostate cancer, two different exosome biomarkers, prostate cancer-associated 3 (PCA-3) and transmembrane serine protease 2 (TMPRSS2), are directly associated with incidence." (PMID 38693223, 2024). "To investigate the effectof 5-H-Y on prostate cancer cell proliferation via AR signaling, we evaluated the mRNA expression levelsof the AR-responsive genes encoding PSA and transmembrane protease,serine 2 (TMPRSS2) after 5-H-Y treatment in LNCaP cells." (PMID 39258898, 2024). "The most common molecular alteration in prostate cancer is the fusion of ERG and TMPRSS2, a widespread event associated with poor prognosis." (PMID 39351232, 2024). "Although there is limited data on TMPRSS2’s role in cancers other than prostate cancer, its interaction with TMPRSS4, known to be overexpressed in several types of cancers, indicates a potential broader role in carcinogenesis." (PMID 39350850, 2024). "It has been shown that NF-κB-mediated oxidative stress can induce de novo genomic rearrangements, as was previously shown for the TMPRSS2-ERG gene fusion in prostate cancer." (PMID 39068468, 2024). "Silencing menin in AR-positive prostate cancer cell lines also reduces the expression of TMPRSS2, an androgen-responsive transmembrane serine protease that promotes prostate cancer growth and metastasis." (PMID 39336822, 2024). "MxA is also frequently deleted in prostate cancer as a consequence of the TMPRSS2‐ERG fusion, which is linked to more aggressive and invasive prostate cancer." (PMID 39285636, 2024).
prostate carcinoma (continued). "The TMPRSS2-ERG fusion gene is the most common genetic alteration seen in prostate cancer with very wide variations across different races, laboratories, cohorts, and zonal origin of the tissue used." (PMID 38730435, 2024). "TMPRSS2 is highly expressed in prostate cancer and contains androgen response elements in the promoter." (PMID 38396898, 2024). "TMPRSS2-ERG (T2E) fusion is highly related to aggressive clinical features in prostate cancer (PC), which guides individual therapy." (PMID 38331878, 2024). "Prostein is the second most common 5′ partner gene in ETS Transcription Factor ERG (ERG) rearrangements in prostate cancer after Transmembrane Serine Protease 2 (TMPRSS2), another constitutively expressed androgen regulated gene in prostate epithelium." (PMID 38218896, 2024). "Previous studies have established that TMPRSS2–ERG fusion is the most frequent genomic alteration in prostate cancer, present in ∼50% of cases, and that TMPRSS2–ERG fusion is an early event in disease progression." (PMID 39347576, 2024). "Studies on TMPRSS2 were mainly conducted in prostate cancer (PC) due to its high expression in prostate epithelium luminal cells: in this respect, cancer cells showed higher TMPRSS2 expression both in primary and advanced or metastatic PCs." (PMID 38254788, 2024). "In that study, which aimed to investigate the role of TMPRSS2-ERG in NO-cGMP signaling in prostate cancer cells, silencing the sGCα1 gene expression was reported to decrease sGCβ1 protein levels without affecting its mRNA expression, and vice versa." (PMID 39337539, 2024). "The relationship of TMPRSS2-ERG with prostate cancer is well studied in in vivo and in vitro models and has been proposed as a new molecular marker for the diagnosis of this pathology." (PMID 39595075, 2024). "The TMPRSS2-ERG fusion gene is the most common genetic alteration seen among prostate cancer patients." (PMID 38730435, 2024). "Many of these proteins, including EWS:FLI1 and EWS:ERG fusions in Ewing sarcoma (EwS) and TMPRSS2:ERG in prostate cancer (PCa), drive oncogenic programs via binding to GGAA repeats." (PMID 38530366, 2024). "The result was similar when comparing ten localized prostate cancers (five TMPRSS2–ERG+ and five TMPRSS2–ERG−) and benign prostate." (PMID 39020220, 2024). "Co-IP of PABPC1 using an anti-ERG antibody in TMPRSS2/ERG-positive VCaP prostate cancer cells demonstrated that endogenous ERG-bound PABPC1." (PMID 37956771, 2023). "In our assessment, we have observed a dearth of studies investigating the dynamic interplay between TMPRSS2 and p300 in prostate cancer." (PMID 37511059, 2023). "The fusion of the androgen‐related transmembrane protease serine 2 gene with the ETS‐related gene (TMPRSS2‐ERG), which accounts for 90% of prostate cancer fusions, has been linked to aggressive tumors with a fatal phenotype and a poor prognosis." (PMID 39188554, 2023). "The androgen-responsive expression of TMPRSS2 has been shown to be regulated by GATA2 in prostate cancer cells." (PMID 37208193, 2023). "TMPRSS2 has been demonstrated upregulated in prostate cancer cells by androgenic hormones and downregulated in prostate cancer tissue which is androgen-independent." (PMID 36992839, 2023). "Among them, TMPRSS2 is a known oncogene that promotes tumor progression and metastasis in prostate cancer." (PMID 36975376, 2023). "Valproic acid (VPA) reduced ACE2 expression in different epithelial and endothelial cell lines, and TMPRSS2 expression in prostate cancer cells." (PMID 38162580, 2023). "TMPRSS2 is a mostly membrane-bound serine-protease that promotes metastasis of prostate cancer and increases expression of some matrix metalloproteinases." (PMID 37278822, 2023). "A TMPRSS2:ERG translocation is detectable in ~50% of all prostate cancer foci, and results in overexpression of ERG (ETS Transcription Factor ERG) from exon 4 to 3′-end in >95% of TMPRSS2:ERG cases." (PMID 36765747, 2023).
prostate carcinoma (continued). "The upregulated plexin-B1 was observed to enhance TMPRSS2-ERG induced prostate cancer-derived VCaP cell migration and invasion." (PMID 37627074, 2023). "The study investigates the regulatory mechanisms involving the prostate cancer-associated long noncoding RNA PRCAT38 and the oncogene TMPRSS2." (PMID 37511059, 2023). "It has been shown that androgens regulate the expression of TMPRSS2, which is the most commonly altered gene involved in primary prostate cancer and a crucial factor in allowing cell infection by coronaviruses, such as SARS-CoV-2." (PMID 37375800, 2023). "TMPRSS2 is a well-known transcriptional target of AR in prostate cancer cells and has recently shown to be regulated by androgens and anti-androgens also in lung cells and mouse lung tissue." (PMID 37287057, 2023). "This study aimed to review the roles of p300 and TMPRSS2 (transmembrane protease, serine 2) in the AR (androgen receptor) pathway as they are closely related to the development and progression of prostate cancer." (PMID 37511059, 2023). "While in some cancer types, like prostate cancer, TMPRSS2 is increased within the cancer tissue and correlates with poor survival rates, TMPRSS2 expression is decreased in lung cancer tissue, which correlates with poor outcomes." (PMID 36830955, 2023). "For example, in prostate cancer, soluble TMPRSS2 is generated by autocatalytic cleavage and released into the circulation." (PMID 37009799, 2023). "Collectively, these findings imply that the overexpression of the ETS transcription factors, resulting from chromosomal rearrangements involving the TMPRSS2 genetic elements, represents a crucial facet of the molecular pathology of prostate cancer." (PMID 37511059, 2023). "We focused on articles that use similar techniques, particularly those that use prostate cancer cell lines and immunohistochemical staining to study the molecular impact of p300 and TMPRSS2 in prostate cancer specimens." (PMID 37511059, 2023). "In a comparison of gene sets related to prostate cancer progression, transmembrane serine protease 2 expression was reduced in PC3-shESS2 cells." (PMID 37524814, 2023). "For example, the prostate cancer fusion TMPRSS2::ERG, identified as our fourth most tumor-enriched fusion (182 of 465 TCGA prostate tumor samples), is also detected in six normal prostate samples (five TCGA and one GTEx)." (PMID 37323575, 2023). "The research highlights the critical involvement of p300 in TMPRSS2 gene expression in response to dihydrotestosterone (DHT), a hormone implicated in prostate cancer progression." (PMID 37511059, 2023). "EVs isolated from the urine of prostate cancer patients have shown the presence of prostate cancer biomarkers, PCA-3 and TMPRSS2:ERG thus showing specific diagnostic and clinical value for the transcriptome within tumor EV." (PMID 37091854, 2023). "Although PTEN loss is less prevalent, it likely represents a more clinically relevant genetic rearrangement than TMPRSS2-ERG fusion in prostate cancer." (PMID 37185705, 2023). "This TMPRSS2:ERG fusion affects approximately half of all prostate cancers and predominates in patients of a younger age." (PMID 37892063, 2023). "Gene fusions between androgen-regulated genes and ERG (e.g., TMPRSS2-ERG) occur in ~50% of prostate cancers, with the alteration resulting in the presence of ERG overexpression in both early and late-stage prostate cancer." (PMID 37377909, 2023). "In this study, we sought to investigate the implication of p300 and TMPRSS2 proteins in the molecular pathology of prostate cancer." (PMID 37511059, 2023).